MICE (MHC class I polypeptide-related sequence E (pseudogene))
Synonyms: dJ377H14.7; PERB11.5
Gene: Transcribed unprocessed pseudogene on chromosome 6 (29,741,731 to 29,748,969, reverse strand). Ensembl gene ENSG00000273340.
Diseases named in the same sentence as MICE in open-access papers:
MICE is named in the same sentence as 1 disease in open-access papers, as found by Europe PMC text mining. Sharing a sentence is not in itself a finding about the gene and the disease.
MICE shares sentences with these, for which no sentence is quoted: Tumor (1 paper).